INS (insulin)
Diseases named in the same sentence as INS in open-access papers (continued):
Sharing a sentence is not in itself a finding about the gene and the disease.
Insulin resistance (continued). "ERαKO mice develop glucose intolerance and have decreased insulin sensitivity because of hepatic insulin resistance." (PMID 30211334, 2018). "The different action mechanisms to modulate insulin resistance and insulin secretion are also influenced by the changes in the contents of isoflavonoid glycans and aglycans, amino acids, peptides and soyasaponins." (PMID 30380669, 2018). "Increased adipocyte size is characteristic of hypertrophy and is an indication of obesity and increased fat mass, which correlates with insulin resistance and aberrant insulin signaling." (PMID 30562363, 2018). "To establish the experimental model of hyperinsulinemia, hyperandrogenism, and hyperandrogenism with peripheral insulin resistance in vivo, we chronically treated rats with insulin and/or hCG." (PMID 29719598, 2018). "Several studies have indicated that fatty acid uptake and fat accumulation in the liver leads to the formation of bioactive lipid intermediates that are able to interrupt insulin signaling, hereby accelerating insulin resistance." (PMID 29510489, 2018). "Insulin secretion increases with age, which is generally attributed as a compensation for age-related insulin resistance." (PMID 29892261, 2018). "Studies have shown that hyperglycemia results in overproduction of ROS, which impairs glucose-stimulated insulin secretion and induces insulin resistance." (PMID 29967794, 2018). "Fasting plasma glucose, insulin, leptin, lipids and homeostasis model assessment of insulin resistance values were measured, and an oral glucose tolerance test was performed." (PMID 30275911, 2018). "Using cultured 3T3-L1 adipocytes, we established a model of physiologically-derived oxidative stress by inhibiting the cycling of glutathione and thioredoxin, which induced insulin resistance as measured by impaired insulin-stimulated 2-deoxyglucose uptake." (PMID 29379070, 2018). "kITT on the other hand, demonstrates that both diabetic groups obtained a lower rate of blood glucose reduction (p<0.05) after insulin application, indicating insulin resistance in diabetic animals." (PMID 29924854, 2018). "Platelet reactivity and increased coagulation increase in concert with systemic insulin resistance, but are also observed acutely after ingestion of a high calorie meal in insulin resistant individuals." (PMID 29209827, 2018). "We have shown that the total body fat mass and subcutaneous abdominal fat are associated with insulin resistance in women with a history of GDM and now add that increased CRP is related to reduced insulin sensitivity." (PMID 29951553, 2018). "Type II diabetes (TIIDM) is characterized by high levels of blood glucose followed by excessive insulin release so that the target cells become less sensitive, developing insulin resistance and maintaining hyperglycemic levels." (PMID 29971166, 2018). "Type 2 diabetes (T2DM) is characterized by two major features: peripheral insulin resistance and impaired insulin secretion from pancreatic beta cells." (PMID 29615971, 2018). "Five weeks after the high fat diet, plasma glucose, insulin and insulin resistance (HOMA index) also increased significantly in the ob/ob mice compared with C56BL/6 J mice." (PMID 29391561, 2018). "The increase in BP was accompanied by increased insulin levels, insulin resistance, and increased levels of endothelin-1." (PMID 29882756, 2018). "An ITT revealed that whole-body insulin sensitivity was impaired in MetS rats, and that this insulin resistance was ameliorated by the low dose of HK L-137." (PMID 29802339, 2018). "Insulin resistance was calculated using the quantitative insulin sensitivity check index (QUICKI) = 1/[log fasting insulin level (μU/ml) + log fasting glucose level (mg/dl)]." (PMID 30055649, 2018). "Several defects in the activity of essential insulin signaling factors have been identified as responsible of insulin resistance in T2D pathogenesis." (PMID 30469501, 2018).
Insulin resistance (continued). "We were especially interested in measuring insulin levels in CSF, as insulin resistance is of great current interest in the field and insulin levels have previously been reported to be altered in the CSF of AD patients." (PMID 29505610, 2018). "Insulin resistance leads to a worse therapeutic response to insulin therapy in patients with chronic HCV infection." (PMID 30186821, 2018). "Adipose tissue, besides skeletal muscle and the liver, is the main tissue responsible for insulin-dependent glucose metabolism, therefore, metabolic disturbances in these tissues lead to the induction of insulin resistance." (PMID 30545025, 2018). "In this study, we demonstrated that UA is able to exert a direct effect on insulin signaling inducing NO synthesis, as observed in condition of insulin resistance." (PMID 29619007, 2018). "Insulin resistance is a hallmark of T2DM, leading to down-regulation of insulin signaling pathways (at the post-receptor level) in these tissues." (PMID 30567565, 2018). "A reduced response to normal insulin concentrations in insulin-sensitive organs, namely, the liver, muscle, adipose tissue, and the heart, reflects insulin resistance." (PMID 29484207, 2018). "NOV regulates various inflammatory molecules, which impair insulin signaling and promote insulin resistance." (PMID 29707604, 2018). "As expected, the consumption of a HFD led to the development of various MS features, including obesity, hyperglycemia, dyslipemia, high levels of plasma insulin, insulin resistance, and NAFLD." (PMID 29367725, 2018). "Partial correction of anemia with erythropoietin was shown to reduce insulin resistance as well as reduce insulin secretion." (PMID 28739553, 2018). "The deterioration of orderly [Ca2+]i oscillations in islets is also believed to contribute to the loss of pulsatile insulin secretion observed in T2DM, which leads to insulin resistance and hyperglycemia." (PMID 29348619, 2018). "In hypertrophied adipocytes, the insulin-dependent glucose uptake is reduced due to deficiency of the GLUT4 receptors, which aggravates hyperglycaemia and insulin resistance." (PMID 30219068, 2018). "More than 50% of patients were thought to have insulin resistance that was demonstrated by elevated fasting insulin levels or a fasting glucose-to-insulin ratio of less than 4.5." (PMID 30373317, 2018). "Typically, insulin resistance is associated with increased plasma FFA concentration, and improvement of insulin sensitivity is accompanied by a decrease in plasma FFA levels." (PMID 30545025, 2018). "Overexpression of Pref-1 in mice promotes a lipodystrophic phenotype and insulin resistance via decreased skeletal muscle glucose uptake and impaired skeletal muscle insulin signalling." (PMID 29760587, 2018). "Previous studies have demonstrated the role of both of these pathways in improving glucose tolerance and insulin sensitivity in insulin resistance condition." (PMID 30627105, 2018). "Elevated plasma levels of FFAs impair insulin signaling and produce skeletal muscle insulin resistance in healthy subjects." (PMID 30011790, 2018). "The majority of obese individuals develop insulin resistance and type 2 diabetes; however, approximately 10–25% of these individuals seem to remain insulin sensitive and metabolically ‘healthy’18." (PMID 30065264, 2018). "Insulin resistance is a condition where fat, muscle, and liver have a lowered response to endogenous or exogenous insulin." (PMID 30775682, 2018). "Due to the large sample size, we observed a very strong negative correlation between adipose GC-A gene expression and insulin resistance, suggesting that low adipose GC-A expression relates to low insulin sensitivity." (PMID 29348496, 2018). "Insulin resistance is due to the impairment of insulin signaling by inflammation, oxidative stress and other factors." (PMID 30041479, 2018).
Insulin resistance (continued). "Treatment of HepG2 cells with high dose insulin induced insulin resistance as indicated by the marked reduction in glucose uptake in insulin-resistant group." (PMID 29786669, 2018). "TNFα neutralization improves peripheral insulin sensitivity in these models, demonstrating a key role of inflammation in the development of insulin resistance." (PMID 29570618, 2018). "Mice with PPARγ knockout in mature cells also develop insulin resistance and hyperlipidemia through dysregulation of molecular pathways of insulin signaling, FFAs uptake, and lipolysis." (PMID 30037087, 2018). "As expected, we found higher insulin resistance and area under the curve (AUC) for glucose and insulin, and lower insulin sensitivity and β-cell function, as assessed by insulin secretion-sensitivity index, in women diagnosed with GDM at weeks 14–16 and 30–32." (PMID 30190548, 2018). "Insulin resistance refers to a condition in which target organs show a reduced responsiveness to insulin." (PMID 29533014, 2018). "In line with our results, some studies found a significant decrease in fasting insulin levels or improvement in insulin resistance following nut consumption." (PMID 30131846, 2018). "While measuring insulin resistance directly or indirectly remains technically difficult in general practice, along with multiple stability issues for insulin, various indirect measures have been suggested by authorities." (PMID 30323862, 2018). "Insulin resistance triggers the dysregulation of neuronal insulin signaling and ultimately leads to cognitive dysfunction." (PMID 30043289, 2018). "Lipotoxicity increases inflammation, reduces insulin signaling and dysregulates the FA metabolism resulting in cardiac insulin resistance." (PMID 30344301, 2018). "When examining metabolic health, studies have demonstrated that sleep restriction reduces whole body insulin sensitivity and insulin resistance at a cellular level." (PMID 30072950, 2018). "Insulin resistance weakens insulin-mediated suppression of lipolysis in adipose tissue, resulting in the release of a large amount of FFAs and glycerol into the circulation." (PMID 30692925, 2018). "Diabetes mainly occurs due to the insufficient secretion of insulin or insulin resistance which leads to elevation of blood glucose level." (PMID 29755552, 2018). "The most precise method for quantitating insulin resistance is the hyperinsulinemic euglycemic clamp technique, because it directly measures the effects of insulin to stimulate glucose utilization under steady-state conditions in vivo." (PMID 30151057, 2018). "Overweight/obese PCOs patients revealed higher insulin resistance and lower insulin sensitivity, and also greater TG and LDL cholesterol." (PMID 30197771, 2018). "To examine the effects of luseogliflozin on insulin resistance in db/db mice, we performed an intraperitoneal insulin tolerance test and found that insulin resistance improved in the luseo group compared with the control group." (PMID 29717223, 2018). "Insulin resistance is initially compensated by increased pancreatic β-cells insulin production in order to maintain fasting euglycemia; this is referred to as a prediabetic stage." (PMID 30274207, 2018). "T2D is characterized by a disorder of insulin action, impaired glucose uptake into skeletal muscle and adipose tissue, and greater hepatic glucose output, resulting in hyperglycemia and insulin resistance." (PMID 29316644, 2018). "SD-FRE promoted GLUT4 expression and activated AMPK phosphorylation in insulin target tissues of KK-Ay mice, contributing to ameliorate insulin resistance in T2DM." (PMID 30061831, 2018). "The decrease of VAT Treg cells with aging is accompanied by a decline in insulin sensitivity, suggesting a protective role of VAT Treg cells in aging-associated insulin resistance." (PMID 30323806, 2018).
Insulin resistance (continued). "ISI and HOMA-IR can be used to evaluate insulin sensitivity and insulin resistance, respectively, but they are only accurate before β-cell failure." (PMID 29670038, 2018). "CFD induced obesity, lipid metabolism disorders, insulin resistance and inhibited the insulin signaling." (PMID 30153273, 2018). "Lipid accumulation and increased systemic inflammation in obesity is known to trigger an imbalance of energy homeostasis and abnormal cellular responses to insulin, leading to insulin resistance and type 2 diabetes (T2D)." (PMID 29783731, 2018). "Decreased GLUT4 expression and cell membrane localization, increased IRS-1 phosphorylation at Ser307 and decreased AKT phosphorylation at Ser473 after insulin stimulation have been well documented in insulin resistance." (PMID 29601606, 2018). "ER stress contributes to glucose disorder in type 2 diabetes by induction of insulin resistance or inhibition of secretion of insulin." (PMID 30374328, 2018). "Fasting blood glucose, insulin, C-peptide, and homeostatic model assessment of insulin resistance (HOMA-IR) were higher in women with GDM." (PMID 30355290, 2018). "Despite information above, DM initiated by insulin resistance and high insulin level in dogs is considered as an uncommon condition." (PMID 29805204, 2018). "The aim of the present study was to examine the effect of RSV on blood glucose level, FOXO1 and FOXO3a expression in adipose tissue, insulin level, insulin resistance and serum superoxide dismutase (SOD) activity in rats with T2DM." (PMID 31565649, 2018). "The mechanistic factors by which CNIs contribute to the development of PLTDM are diverse and include deregulation of insulin secretion, apoptosis of insulin-producing beta cells and induction of peripheral insulin resistance." (PMID 29411291, 2018). "Adipose tissue insulin resistance is mainly related to the inability of insulin to inhibit HSL activity." (PMID 30545025, 2018). "Cigarette smoking and tobacco exposure lead to increased insulin resistance and decreased effectiveness of insulin." (PMID 29255620, 2018). "This conclusion is also supported by a small study showing significantly higher insulin resistance in young Roma compared with Slovaks of the same age and in another study of the same authors showing higher insulin levels in Roma participants in BMI ≥25." (PMID 30469436, 2018). "Reduction of insulin levels is an important aspect given that hyperinsulinemia and insulin resistance are commonly observed in obesity with adipokine alterations, conditions associated with increased risk of BC and poor prognosis." (PMID 30363988, 2018). "IMAT was regressed separately against fasting serum glucose concentrations, insulin, homeostatic model assessment-insulin resistance (HOMA-IR), and lipids and lipoproteins." (PMID 30254672, 2018). "The etiology of T2DM mainly reflects in defects of insulin secretion and insulin resistance development." (PMID 30595798, 2018). "As previously reported, pregravid obesity resulted in increased plasma levels of metabolic hormones such as insulin, leptin, and lipocalin-2, indicative of insulin resistance, mild gestational hyperglycemia, and metabolic syndrome." (PMID 30131724, 2018). "Insulin resistance, defined as a subnormal biological response to the glucose-lowering effect of insulin, is a characteristic of many common disorders, including type 2 diabetes, the metabolic syndrome, fatty liver disease, and obesity." (PMID 30034366, 2018). "Chronic HS feeding also produces insulin resistance in adult flies, and flies with a compromised gut barrier exhibit impaired insulin signaling, with a reduced degree of Akt phosphorylation, despite increased insulin receptor expression." (PMID 30504122, 2018). "Hepatic deletion of Akt1 and Akt2 isoforms resulted into glucose intolerance, insulin resistance and a defective insulin transcription in response to feeding." (PMID 30469501, 2018).
Insulin resistance (continued). "Lower dependence on insulin-stimulating therapies can also prevent hyperinsulinemia-driven insulin resistance and obesity." (PMID 30520733, 2018). "It is suggested that increasing age, BMI and energy intake not only decrease the effectiveness of insulin signaling pathways that result in decreased insulin sensitivity and increased insulin resistance, but also affect serum 25(OH)D levels." (PMID 32153911, 2018). "Osteocalcin−/− knockout mice have exhibited increased fat mass and insulin resistance and decreased expression of insulin target genes and adiponectin genes." (PMID 30083134, 2018). "What leads to this switch in the insulin pathway observed in insulin resistance and AD remains to be elucidated." (PMID 29743868, 2018). "Consistent with this, the aging‐associated increases in fasting serum insulin level, fed insulin level, and HOMA‐IR index (a quantitative analysis to measure insulin resistance) were also partially inhibited in the age‐matched Tie2‐CYP2J2‐Tr mice." (PMID 29318723, 2018). "By contrast, there was little or no increase in the ratio of pIR/IR or pIRS-1/IRS-1 in HFD-fed mice following insulin injection, indicating central insulin resistance." (PMID 29910467, 2018). "It has been reported that patients with AD have high insulin resistance, which indicates increased insulin levels and reduced binding efficacy on neuronal synapses and astrocytes." (PMID 30400348, 2018). "Some of these cytokines/chemokines were shown to impair insulin action in normally insulin-sensitive tissues, leading to insulin resistance." (PMID 29799467, 2018). "Both increased peripheral insulin resistance and failed compensation of insulin need are hallmarks of GDM." (PMID 30355290, 2018). "Insulin sensitivity was evaluated using homeostatic model assessment for insulin resistance (HOMA IR)." (PMID 30474555, 2018). "To test these two components of insulin resistance, we performed mouse clamps and cell culture experiments at lower and higher insulin doses." (PMID 30047243, 2018). "Under the condition of insulin resistance, normal pancreatic β cells increase the production of insulin to maintain blood glucose levels." (PMID 30574122, 2018). "In insulin resistance state, the pancreas compensates to increase the production of insulin to maintain normal glucose levels." (PMID 29593573, 2018). "Because increased lipid accumulation and inflammation are correlated with insulin resistance, insulin signaling pathways were further analyzed." (PMID 29961765, 2018). "Ginsenosides in red ginseng are known to prevent insulin resistance by activating insulin signaling in cells, animals and humans." (PMID 30041479, 2018). "Insulin resistance represents a decreased sensitivity and reactivity of target tissues to insulin in maintaining the balance and stability of body's glucose level." (PMID 30420897, 2018). "GLUT4 trafficking is frequently disrupted in T2DM, leading to a pathological condition termed insulin resistance (IR): In this case, cells fail to respond normally to insulin, which finally results in hyperglycemia." (PMID 30314325, 2018). "Higher levels of Vitamin D correlated negatively with insulin resistance in a cohort of Chinese men and women with T2DM, while raising Vitamin D levels in South Asian women with insulin resistance has been shown to improve insulin sensitivity." (PMID 29710852, 2018). "Insulin resistance is the prediabetic state where insulin sensitive tissues such as muscles and fat show reduced insulin sensitivity and a decrease in glucose uptake (GU)." (PMID 30248999, 2018). "SD-FRE promoted GLUT4 expression and activated AMPK phosphorylation in insulin target tissues (muscle, adipose tissue and liver) of KK-Ay mice, thus facilitating glucose utilization to ameliorate insulin resistance." (PMID 30061831, 2018).